FTO (FTO alpha-ketoglutarate dependent dioxygenase)
Diseases named in the same sentence as FTO in open-access papers (continued):
Sharing a sentence is not in itself a finding about the gene and the disease.
Obesity (continued). "In 2007, the fat mass and obesity (FTO)‐associated gene was first identified during a GWAS study focusing on diabetes as a susceptible obesity gene." (PMID 38973101, 2024). "The first identified obesity-susceptibility locus was the FTO gene (fat mass obesity associated) and until now this gene is recognized as the highest contributor to the risk of obesity." (PMID 38672494, 2024). "For instance, previous studies have highlighted the attenuating effects of physical activity on the association between the FTO polymorphism and obesity risk." (PMID 39858551, 2024). "Using the 2,342 m5C sites derived from HeLa cells or the 3,965 mRNA sites from our union set yielded seven RBPs enriched in both comparisons, the five seen before plus FTO (Fat mass and obesity associated) and AKAP1 (A-kinase anchoring protein 1)." (PMID 38986569, 2024). "On the other hand, genome-wide association studies found that the fat mass and obesity-associated gene (FTO) is involved in several metabolic diseases." (PMID 39758312, 2024). "A meta-analysis of eight studies compromising 2441 cases and 1668 controls found that the FTO gene variant rs9939609 was associated with increased obesity risk, and the A allele was considered to be a risk factor for obesity susceptibility in adults." (PMID 39257882, 2024). "Last but not least, to mitigate the potential pleiotropy associated with obesity, SNPs near the FTO gene were excluded from our restricted model." (PMID 38731833, 2024). "Genetic variants in an IRX3 enhancer (FTO locus) are reproducibly associated with obesity and type 2 diabetes, though depot-specific roles for IRX3 have not been explored." (PMID 39401200, 2024). "Previous studies demonstrated this contribution of FTO rs17817449 SNP with obesity but there was controversy regarding the risk allele of FTO rs17817449 SNP involved in obesity development." (PMID 39706986, 2024). "The FTO rs17817449 GT and TT genotypes, as well as TGs level, were identified as independent risk factors for predicting overweight and obesity in DS children." (PMID 39706986, 2024). "At the same time, the effect of overweight and obesity on the association of GWAS-significant loci (rs8044769 FTO and rs143383 GDF5) with KOA has been examined only in a small number of studies." (PMID 38424630, 2024). "The results have suggested a strong association between FTO 30685T/G and -23525T/A polymorphisms with obesity and related phenotypes in the studied population." (PMID 39253342, 2024). "The fat mass and obesity-associated protein (FTO), known for its association with body mass and obesity, influences the energy metabolism of cancer cells." (PMID 39723162, 2024). "The consumption of energy-rich or high-fat products presented by the holders of this variant of the FTO gene can favor excessive energy supply, which in turn can lead to obesity." (PMID 39458556, 2024). "Although a strong positive association between these FTO “risk SNPs” (including rs1421085 T>C) and obesity is reported across human populations of diverse ancestry, relatively weak (even none) significant associations have been observed in African populations." (PMID 39873006, 2024). "The aim of this study was to analyze the effects of genotypes and haplotypes of the fat mass and obesity-associated (FTO) and melanocortin 4 receptor (MC4R) genes on total body weight loss (TBWL), post-surgery weight, and post-BMI after bariatric surgery." (PMID 38674326, 2024). "Specifically, the dysregulation of m6A patterns, via disruption of demethylase FTO is linked to the pathophysiology of obesity and systemic metabolism." (PMID 38363215, 2024). "For the allele A rs9939609 FTO gene, individuals who consume high amounts of fat in their diet will have a higher risk of obesity." (PMID 39458556, 2024).
Obesity (continued). "Specifically for the T>A rs9939609 polymorphism of the FTO gene (with three possible genotypes, TT, AT and AA), each copy of the minor A allele is associated with a 31% increase in obesity risk and an average higher body weight of approximately 1.2 kg." (PMID 39858551, 2024). "The 2007 discovery of SNPs in the FTO gene locus, linked to BMI and obesity risk across various populations, marked FTO as the first gene definitively linked to obesity." (PMID 39192357, 2024). "For instance, variations in the FTO gene have been associated with differential responses to macronutrient intake and susceptibility to obesity." (PMID 39203810, 2024). "A locus within an intron in the FTO gene, whose variants are reproducibly associated with obesity and type 2 diabetes, is actually an enhancer for the mesodermal developmental transcription factor IRX3." (PMID 39401200, 2024). "To date, nine mammalian homologs of AlkB are known, namely ABH1–8 and FTO (fat mass and obesity-associated protein, also known as ABH9)." (PMID 39329974, 2024). "Herein, we find that m6A modification is increased during ferroptotic cell death and correlates with the decreased m6A demethylase fat mass and obesity-associated protein (FTO) expression." (PMID 38600610, 2024). "A meta‐analysis that examined the link between the FTO gene polymorphisms and obesity risk in the Chinese population found a significant association between FTO SNPs and increased obesity risk, with a pooled odds ratio of 1.30." (PMID 38556726, 2024). "Of the three SNPs associated with both weight change and lifespan, two (rs429358 and rs7412) are variants in the APOE gene, and rs1085251 is a known obesity association in the FTO locus." (PMID 38987242, 2024). "For example, genetic susceptibility, in conjunction with genes such as FTO, affects appetite regulation and energy expenditure, ultimately leading to obesity." (PMID 39439567, 2024). "Various studies indicate the role of FTO in the susceptibility to obesity as it increases adipogenesis by regulation of various adipogenic pathways and adipocyte differentiation." (PMID 39600630, 2024). "The enzymes involved in m6A RNA methylation, including methyltransferase‐like protein 3 and 14 (Mettl3, Mettl14), as well as demethylase, fat mass and obesity‐associated (FTO) were further examined." (PMID 39445711, 2024). "Following its identification as an m6A demethylase, research has uncovered molecular links between FTO’s activity and obesity susceptibility." (PMID 39192357, 2024). "The biochemical role of the FTO gene in predisposition to obesity has been discussed in many previous studies." (PMID 39706986, 2024). "Some studies have concluded that variations in the first intron of FTO cause differences in methylation capacity, and that methylation status regulates the development of obesity and related diseases." (PMID 39483856, 2024). "Based on previous promising findings, the present study seeks to explore the interactions between bioactive compounds found in Little Millet and the fat mass and obesity-associated (FTO) protein." (PMID 39494311, 2024). "The FTO rs9939609 variant increases the risk for class III obesity 3.54 times, and physical inactivity increases the risk 6.37 times." (PMID 38610209, 2024). "In this study, we tried to find out the impact of FTO variants 30685T/G (rs17817449) and -23525T/A (rs9939609) on the development of obesity risk." (PMID 39253342, 2024). "On the other hand, FTO rs17817449 (GT + TT), TT genotypes and TGs were considered independent risk factors for overweight and obesity prediction in DS children in multivariate analysis." (PMID 39706986, 2024). "The protein fat-mass-and-obesity-associated (FTO) is present in various metabolic active tissues: the heart, kidneys, fatty tissue, and brain." (PMID 39057584, 2024).
Obesity (continued). "The gene encoding the alpha-ketoglutarate-dependent dioxygenase (ALKBH9), popularly known as the fat mass and obesity-associated gene (FTO), is widely recognized for its role as a genetic factor predisposing to obesity." (PMID 39080362, 2024). "The FTO protein, which is associated with adiposity and obesity, can decrease the concentration of m6A in mRNA transcripts, thereby regulating the expression of target genes such as ASB2 and RARA." (PMID 39295872, 2024). "Previous studies have established a significant association between several genes and obesity, such as the fat mass and obesity-associated (FTO) gene, melanocortin-4 receptor (MC4R) gene, and leptin receptor (LEPR) gene." (PMID 38674446, 2024). "The first defined obesity susceptibility gene with a more significant influence on body mass to date was the fat mass and obesity-associated (FTO) gene." (PMID 39336728, 2024). "For example, fat mass and obesity-associated (FTO) gene is essential for insulin secretion and beta-cell function, as indicated in in vitro studies using INS-1 cells and human pancreatic islets." (PMID 39769194, 2024). "In the present study, the T allele of FTO rs17817449 polymorphism was a risk allele (OR: 2.139) for developing overweight/obesity among DS children." (PMID 39706986, 2024). "The study revealed that a risk allele of the FTO gene rs9939609 variant was significantly associated with obesity and CHD." (PMID 39257882, 2024). "Various studies conducted on different populations have revealed different levels of association between FTO gene SNPs and obesity." (PMID 38973101, 2024). "Another study reported that one genetic variant (rs9939609) in the fat mass and obesity-associated (FTO) gene increased obesity risk among Kuwaiti adults." (PMID 39544590, 2024). "Fat mass and obesity-associated (FTO) is a ubiquitous DNA repair enzyme homolog of the AlkB family of Fe(II)/α-Ketoglutarate-dependent dioxygenases." (PMID 39040764, 2024). "One pathway of the FTO effect on adiposity is by influencing dopamine signaling, given that FTO variants associated with obesity are also associated with several behaviors or disorders dependent on dopamine." (PMID 39130748, 2024). "Several m6A-specific erasers, AlkB homolog 5 (ALKBH5), and fat mass-and obesity-associated protein (FTO) have been discovered." (PMID 39136000, 2024). "The FTO variant linked to human obesity lies in a CRE that also affects the expression of multiple neighboring genes in the TAD through long range regulatory contacts, highlighting the fact that individual CREs can affect broader genetic programs." (PMID 38979203, 2024). "The association between BMI and TC is believed to be linked to shared hormonal and metabolic factors related to central adiposity, as well as potential interactions with genetic variants of the fat mass and obesity-associated (FTO) gene." (PMID 38611106, 2024). "The expressions of GAS5, fat mass and obesity-associated protein (FTO), insulin-like growth factor 2 mRNA-binding protein 2 (IGF2BP2), and Quaking (QKI) were assessed by quantitative reverse transcription-polymerase chain reaction (qRT-PCR) and western blot." (PMID 38782769, 2024). "An early FTO gene variant was discovered as an obesity-susceptible gene in different ethnic populations." (PMID 39257882, 2024). "Among the hundreds of obesity-associated genes, FTO has been identified as the most robust predictor of polygenic obesity [21••]." (PMID 38806863, 2024). "For instance, the FTO gene was the first to be identified by genome‐wide association studies (GWAS) as a known and prominent contributor to polygenic obesity at a population level." (PMID 37034567, 2023). "GWAS have shown that the A allele of the intron FTO variant rs9939609 increases the risk of obesity." (PMID 37238719, 2023). "The fat mass and obesity-associated (FTO) gene, located on chromosome 16q12.2 in intron 1, is a crucial gene linked to obesity pathogenesis." (PMID 38057923, 2023).
Obesity (continued). "In this review, we summarize the current state of knowledge on the fat mass and obesity-associated (FTO) gene and its role in obesity." (PMID 37200795, 2023). "Variation of the fat mass and obesity-associated protein (FTO) is associated with obesity and low concentration of leptin." (PMID 37612540, 2023). "Another large-scale meta-analysis showed that the homozygous FTO risk allele was associated with a 23% higher risk of obesity." (PMID 37697388, 2023). "Epidemiological studies have demonstrated a strong association between FTO SNPs or overweight/obesity and the risk of various types of cancers, such as breast, prostate, kidney, and pancreatic cancers." (PMID 38129517, 2023). "Genes expressed in a lower extent in active beige adipocytes as compared to white ones were overrepresented in several pathways, such as AMPK signaling and TGF-beta signaling only in FTO obesity-risk allele carriers." (PMID 37416800, 2023). "Children were also genotyped for a DNA polymorphism associated with energy intake and obesity (FTO rs9939609) to examine the influence of obesity risk on behavioral and brain responses to food." (PMID 37145386, 2023). "Previous studies have indicated that FTO not only regulated obesity but was also significantly associated (p < 0.05) with economic traits in pigs, sheep, and cattle." (PMID 37835645, 2023). "Children carrying the minor allele ‘A’ at the fat mass and obesity-associated protein (FTO) gene have higher obesity prevalence." (PMID 36979984, 2023). "Among these, many were well known and had been previously associated with BMI and other obesity traits, such as FTO, MC4R, and other loci." (PMID 36658113, 2023). "Active beige adipocytes with FTO obesity-risk alleles had lower expression of mitochondrial complex subunits I, II, and IV as compared to the risk-free carriers." (PMID 37416800, 2023). "The FTO gene is not only an obesity-susceptibility gene, it also affects growth, particularly postnatal growth." (PMID 37943827, 2023). "FTO has been found to act as an ‘eraser′ for m6A demethylation and has been linked not only to an increase in body mass and obesity but also to oncogenesis." (PMID 36718644, 2023). "Although the FTO gene was primarily found to be related to obesity and higher BMI (body mass index) risk, abundant expression of FTO in the brain led to subsequent association studies with affective disorders or completed suicide." (PMID 36983683, 2023). "The molecular docking assay focuses on specific receptors such as human inducible nitric oxide synthase (iNOS), human pancreatic lipase, human reactive oxygen species (ROS) 1 kinase, and fat mass and obesity-associated (FTO) proteins." (PMID 37764670, 2023). "FTO has long been associated with obesity according to early genome-wide association studies and plays a regulatory role in adipogenesis." (PMID 36352530, 2023). "Dietary fat intake modified the association between the FTO genotype and changes in insulin sensitivity and obesity." (PMID 36875367, 2023). "In this sense, the presence of genetic variants in FTO associated with increased risk of obesity is also influencing higher IRX5 mRNA levels in adipocytes, causing decreased energy expenditure and increased lipid accumulation." (PMID 37019912, 2023). "The FTO gene was initially reported as an obesity-susceptibility gene that predisposes individuals to obesity." (PMID 38020896, 2023). "The fat mass and obesity-associated (FTO) gene was the first obesity-susceptibility gene identified through a genome-wide association study (GWAS)." (PMID 37238719, 2023). "We also observed lower expression of GPT2 in active and inactive beige adipocytes with FTO obesity-risk genotype as compared to risk-free allele carriers." (PMID 37416800, 2023). "This study aimed to examine the interaction of Dietary Inflammatory Index (DII) and fat mass and obesity-associated gene (FTO) single-nucleotide polymorphisms (SNPs) on change in obesity measures." (PMID 38618529, 2023).
Obesity (continued). "Further, high-risk males who were homozygous for the obesity-associated allele of an FTO SNP had higher BMI during late adolescence compared to those who carried the minor allele." (PMID 38389820, 2023). "FTO was not only the first identified obesity risk gene, but it was the first discovered m6A demethylase that catalyzes methyl group removal from the N6 position of adenosine residues." (PMID 37238719, 2023). "Recent studies have shown that PCOS women have a higher risk of obesity and type 2 diabetes mellitus due to a common single nucleotide polymorphism (SNP) (rs9939609) of the FTO gene with a T to A change." (PMID 37710301, 2023). "Genetic obesity risk based on FTO SNPs has been shown to have a larger effect on BMI in infrequent drinkers: about twice as large in those who never drank alcohol compared to every-day drinkers." (PMID 38389820, 2023). "For instance, GWAS identified variants in the intron region of the fat mass and obesity-associated (FTO) gene, initially linked to type 2 diabetes, and later associated with obesity, metabolic syndrome, and subsequently, CVD." (PMID 37702886, 2023). "Epidemiological evidence suggesting a close association of NAFLD with obesity suggests the potential role of FTO in the development of NAFLD." (PMID 36717943, 2023). "The upregulation of FTO has been robustly associated with increased BMI and predisposition to obesity and T2DM." (PMID 37252693, 2023). "Of note, FTO expression is closely related to weight gain and obesity, both representing known risk factors for EC." (PMID 35731272, 2023). "Several reports from different populations indicate an association of some variants of FTO with obesity in children and adults." (PMID 36983642, 2023). "Interactions of FTO rs17817449 polymorphism with obesity and other factors on the risk of T2DM and dyslipidemia." (PMID 38161971, 2023). "CRC, as well as breast, pancreatic, and prostate cancers, are associated with the rs9939609 polymorphism of the fat mass and obesity-associated (FTO) gene." (PMID 37545585, 2023). "Active beige adipocytes with FTO obesity-risk alleles had lower level of ETO-R oxygen consumption as compared to risk-free carriers." (PMID 37416800, 2023). "The less expressed genes in active beige adipocytes as compared to white ones were overrepresented in several pathways, such as axon guidance or longevity regulating only in FTO obesity-risk genotype carriers." (PMID 37416800, 2023). "FTO, an obesity gene previously associated with HF13, was associated with unindexed LV mass, but not LVMI." (PMID 36944631, 2023). "The FTO gene, expressed widely with the highest levels in the hypothalamus, is associated with obesity." (PMID 37710301, 2023). "The effect of FTO SNPs on obesity risk and the prevalence of FTO risk alleles has since been shown to vary across different ethnic populations, with the risk of obesity per risk allele increasing 1.25-fold in Asians and 1.15 in Indians." (PMID 37664850, 2023). "FTO is also known as the “obesity risk gene” because its dysregulation, particularly via common SNP variants, has been associated with obesity." (PMID 38389820, 2023). "Relationships of the polymorphisms in fat mass and obesity-associated gene (FTO) and peroxisome proliferator-activated receptor delta gene (PPARD) with metabolic-related diseases remain to be clarified." (PMID 38161971, 2023). "In 2007, the fat mass and obesity–associated (FTO) gene was reported as closely associated with body mass index (BMI) and obesity susceptibility." (PMID 37238719, 2023). "The FTO-encoded protein is involved in multiple molecular pathways contributing to obesity as well as other metabolic complexities." (PMID 37200795, 2023). "The present study shows a wide evaluation of FTO genetic variants associated with a classic indicator of overweight and obesity, which highlights the importance of genetic analyses in the study of obesity." (PMID 36672899, 2023).